IL13 (interleukin 13)
Diseases named in the same sentence as IL13 in open-access papers (continued):
Sharing a sentence is not in itself a finding about the gene and the disease.
Sepsis (continued). "In our study, IL‐13 production in ILC2s was higher than in T cells in both sham and sepsis mice." (PMID 39016179, 2024). "Given the abundance of mitochondria in slow muscle fibres, we hypothesized that an increase in intramuscular IL‐13 would contribute to regulating protein synthesis in slow muscle of PD‐1 KO mice following sepsis." (PMID 39016179, 2024). "Also, significantly lower levels of IL-4 (p<0.0001), IL-10 (p<0.0001), and IL-13 (p<0.05) were measured/detected in children with sepsis compared to children with clinical malaria." (PMID 35811678, 2022). "In the present study, we detected the expression level of IL-13 in the heart after sepsis over time and found that the expression of IL-13 was not simply a phenomenon of increase or decrease in the early stages of sepsis." (PMID 34616745, 2021). "In addition, IL-33, IL-13, and IL-5 have also been reported to prevent acute lung injury during sepsis." (PMID 34616745, 2021). "A more unified view is that IL-13 plays a protective role during sepsis." (PMID 34616745, 2021). "For example, IL-13 could prevent and treat sepsis-induced brain dysfunction by enhancing the mitochondrial function and content in the brain microglia." (PMID 34604237, 2021). "The aim of the present study was to explore the effect of IL-13 on the heart during sepsis." (PMID 34616745, 2021). "Although IL-13 is known to have a protective effect in various diseases, whether IL-13 also has a cardioprotective effect in sepsis remains to be defined." (PMID 34604237, 2021). "In this study, we investigated the expression level of IL-13 at different times after intraperitoneal (i.p.)injection of lipopolysaccharide (LPS), knowing that it could simulate endotoxemia during the sepsis state." (PMID 34616745, 2021). "In mice, IL-13 has been shown to exert a protective role during sepsis by reducing inflammation." (PMID 33053762, 2020). "Our concept requires further investigation; however, our research findings provide new insights into the role of ILC2s in the pathophysiology of sepsis-induced lung inflammation, particularly regarding the possibility of inhibiting IL-13 production in ILC2s by PD-1." (PMID 33053762, 2020). "A Spanish study on 48 children with sepsis found significantly lower IL-13 levels in patients six hours after onset of refractory shock, while a British study in 31 adults observed a correlation of TNF-α and IL-13 levels and a high level of each with septic shock." (PMID 30759882, 2019). "Similar to findings obtained with sepsis-surviving Il1rl1−/− mice, the production of IL-4 and IL-13 was markedly reduced in the lungs of Stat6−/− mice on day 15 after CLP, indicating that these type 2 cytokines can induce their synthesis in a positive feedback loop in an STAT6-dependent manner." (PMID 28374774, 2017). "Moreover, sepsis-surviving Rag1−/− mice showed similar levels of IL-4 and IL-13 in the lungs as those found in sepsis-surviving WT mice." (PMID 28374774, 2017). "Also, increased production of IL-4 and IL-13, as well as M2 polarization, is maintained in sepsis-surviving Rag1−/−mice." (PMID 28374774, 2017). "Moreover, we show that IL-33 induces the expansion of ILC2 populations and the subsequent production of IL-4 and IL13, which together with IL-33 induce a pronounced macrophage reprogramming toward an M2-like phenotype in sepsis-surviving mice." (PMID 28374774, 2017). "IL4 and IL13 are anti-inflammatory cytokine that increase in sepsis and may play important roles in immune regulation." (PMID 26064774, 2015). "This included traditionally evaluated cytokines (IL-1β, IL-6, IL-8, IL-10 and TNF-α) and a number of cytokines that are not commonly associated with sepsis (IL-7, IL-13, IFN-γ and MCP-1)." (PMID 17448250, 2007).
Sepsis (continued). "According to previous research, narcolepsy patients tend to secrete higher levels of cytokines, including IL-2, tumor necrosis factor, IL-4, and IL-13, which could be the reason for narcolepsy being a protective factor against severe sepsis and 28-day mortality in sepsis patients." (PMID 38343642, 2024). "In addition, it is known that IL-33 is a potent activator of type 2 Innate Lymphoid Cells (ILC2), which results in enhanced production of the key effector cytokines IL-5 and IL-13, and that IL-33 plays a major role in local inflammatory changes in the lung, early after the onset of sepsis." (PMID 38279209, 2024). "IL‐13 may be a promising factor critical in treating sepsis‐induced muscle weakness." (PMID 39016179, 2024). "Therefore, blocking PD-1/PD-L1 signaling may lead to increased IL-13 production and the development of new therapeutic strategies for sepsis-induced acute lung injuries." (PMID 33053762, 2020). "IL-13 could exert a protective effect against sepsis by suppressing local inflammation, as shown by the previous study that antibody-mediated inhibition of IL-13 in the sepsis model increased macrophage inflammatory protein-2, macrophage inflammatory protein-1α and TNF-α levels." (PMID 33679715, 2020). "Our results point to the potentially important role of IL‐13‐producing skeletal muscular ILC2s and PD‐1‐mediated suppression of the ILC2 in the pathogenesis of sepsis‐induced ICU‐AW." (PMID 39016179, 2024). "A blockade of IL‐13 led to increased mortality and severer lung injury in a mouse model of CLP‐induced sepsis." (PMID 39016179, 2024). "Here, we analyzed a panel of 47 parameters related to immunothrombosis in sepsis patients and found that patients with confirmed SARS-CoV-2 infection had higher levels of IP-10, MCP-1, and IL-13." (PMID 36980378, 2023). "Subsequently, we explored the protection mechanism of IL-13 in sepsis-induced cardiomyopathy through inhibiting the apoptosis of cardiomyocytes, and found that type 2 innate lymphocyte (ILC2) was the main source of IL-13." (PMID 34616745, 2021). "IL-5 and IL-13, representative type 2 cytokines produced by ILC2, have been shown to protect against lung injury and sepsis." (PMID 33053762, 2020). "It was suggested that the serum levels of IL-6, IL-8, and TNF-α were significantly higher whereas those of IL-10, IL-13, and TGF-β were significantly lower in the sepsis group than those in the sham group." (PMID 31830649, 2020). "Furthermore, the roles played by IL-13 in sepsis also remain unclear." (PMID 33053762, 2020). "A study in CLP-induced sepsis has shown the increase in ILC2s in the peritoneum and small intestine along with the increased IL-13 and IL-33 levels in the peritoneal lavage fluid (PLF) within 24 h post sepsis development." (PMID 32849610, 2020). "In sepsis, increased plasma levels of inflammatory cytokines, including TNF-α, IFN-γ, IL-13, participated in damaging the intestinal barrier function." (PMID 31354386, 2019). "Concentrations of IL-1β, IL-6, IL-7, IL-8, IL-10, IL-13, interferon-γ, MCP-1 and tumour necrosis factor-α were significantly higher in septic shock patients than in those with severe sepsis." (PMID 17448250, 2007). "In contrast, the severe group showed enrichment in pro-inflammatory and immune-activating pathways such as PI3K, IL8, IL-4, IL-13, ERK, and VEGF signaling play key roles in acute and chronic inflammation, contributing to diseases such as meningitis, pneumonia, sepsis, and urinary tract infections." (PMID 41417796, 2025). "Accordingly, these results suggest that IL‐13 expression is enhanced in ILC2s of skeletal muscle in sepsis and further augmented in the absence of PD‐1 signaling." (PMID 39016179, 2024). "Interestingly, IL-4 and IL-13 signaling was also persistently upregulated in non-survivors; this could be reflective of a transition towards Type-2 immunity, which could occur during increased pathogen burden and is associated with poor outcomes in sepsis." (PMID 37822940, 2023).
Sepsis (continued). "Consistent with adult studies, children with hyperferritinemic sepsis had a hypercytokinemia profile reflective of macrophage activation without a commensurate Th2 response (low IL-4 and IL-13)." (PMID 37674218, 2023). "However, both Il-33−/− and Il1rl1−/− mice exhibited reduced levels of IL-9 and IL-13 in plasma and bronchoalveolar lavage fluid (BALF) after sepsis as compared with those in WT mice." (PMID 29511181, 2018). "Although sepsis-surviving Il1rl1−/− mice had higher production of IL-33 than WT mice, they failed to produce more IL-4 and IL-13 in the lungs compared to the naive control mice at day 15 after CLP." (PMID 28374774, 2017). "Nevertheless, we observed an increasing production of type 2 cytokines (IL-4 and IL-13) and IL-33 in the lung tissue homogenates and bronchial lavage (BAL) fluids of sepsis-surviving mice at later time points, starting at day 3 after CLP and remaining elevated over the course of observation." (PMID 28374774, 2017). "No significant changes were observed in IL-1β, IL-2, IL-4, IL-13, GM-CSF, FGFbasic or GM-CSF in caPI3K Tg mice in the presence or absence of sepsis (data not shown)." (PMID 23028587, 2012). "We compared cytokine concentrations among patients with severe sepsis and septic shock, and observed that concentrations of IL-1β, IL-6, IL-7, IL-8, IL-10, IL-13, IFN-α, MCP-1 and TNF-α were significantly increased in septic shock as compared with severe sepsis." (PMID 17448250, 2007). "Interestingly, non-septic ICU patients showed higher plasma levels of IL-13 and IL-27 than the sepsis and the SS groups." (PMID 35327327, 2022). "In sepsis, PD‐1 KO, but not WT, mice showed a tendency of increasing ILC2‐derived IL‐13." (PMID 39016179, 2024).
colorectal cancer (41 papers, 2016 to 2025). A primary or metastatic malignant neoplasm that affects the colon or rectum. "The IVW method was employed to examine the association between eosinophils regulated by gene IL-4, IL-5, IL-13, IL-4R, and IL-5RA and the risk of colorectal cancer and skin malignancies." (PMID 39181688, 2024). "The analysis revealed a negative correlation between eosinophils regulated by IL-4, and IL-13 and the risk of colorectal cancer (P < 0.05)." (PMID 39181688, 2024). "The analysis revealed a negative correlation between eosinophils regulated by IL-4, IL-5, and IL-13 and the risk of colorectal cancer (P < 0.05)." (PMID 39181688, 2024). "For instance, in certain contexts, IL-13 has been associated with promoting conditions favorable to cancer, such as through ROS-induced prooxidative environments linked to colorectal cancer progression 47-49." (PMID 39132165, 2024). "Through the use of MR analysis, our study revealed an inverse association between IL-4, and IL-13-regulated eosinophils and the risk of colorectal cancer in both cohorts." (PMID 39181688, 2024). "Recently, IL-4 and IL-13 and their receptors (IL-4R and IL-13R) have been shown to be increased in colorectal cancer tissues, and this elevation was also shown to be associated with local metastasis." (PMID 32931721, 2020). "The utilization of drugs targeting IL-4, and IL-13, which regulate eosinophils, may potentially elevate the risk of colorectal cancer." (PMID 39181688, 2024). "However, elevated levels of IL-13 are associated with better overall survival compared to low IL-13 levels in colorectal cancer, and further studies revealed anti-tumor effects of IL-13 in vivo." (PMID 39411143, 2024). "Consequently, it is plausible that drugs targeting IL-4, and IL-13 may elevate the risk of developing colorectal cancer." (PMID 39181688, 2024). "The results showed that, compared with normal tissues, the expression of ADRA1B, CDKN2A, FCER2, and IL13 was significantly upregulated in colorectal cancer tissues, while CALM1, CTNNA1, GSR, INSR, and MAPK9 were significantly downregulated." (PMID 40696679, 2025). "It has been reported that ILC2s exert an essential role in the tumour-driven IL-33/ST2/IL-13 axis by promoting the migration and invasion of colorectal cancer cells, which are key factors promoting metastasis." (PMID 38662248, 2024). "A recent study revealed ILC2s to be the major source of IL-4 and IL-13 in tumours in a mouse model of colorectal cancer (CRC), and that ILC2-derived IL-4 and IL-13 promote M-MDSC expression both in vitro and in vivo." (PMID 38464388, 2024). "Studies in human colorectal cancer organoid lines revealed that while tuft cells were present in a small proportion of established lines, IL-13 was dispensable for their maintenance." (PMID 37863104, 2024). "Reports showed that IL-13R is involved in the local metastases process of colorectal cancer, while expression of IL-13 has an impact on survival." (PMID 37176567, 2023). "We investigated the use of a IL-13/IL13Rα2 binding motif, called D1, as a new target for the development of therapeutic monoclonal antibodies (mAbs) for colorectal cancer (CRC) metastasis." (PMID 33917458, 2021). "Together, these results support the capacity of D1-specific mAbs for blocking IL-13-triggered cell invasion, migration and adhesion in colorectal cancer cell lines positive for IL13Rα2 expression." (PMID 33917458, 2021). "In colorectal cancer cells, IL13 induced epithelial-to-mesenchymal transition through the STAT6 pathway and was reversed with knock-down of IL13Rα1." (PMID 33419470, 2021). "The bulk of existing studies on claudin-2 in the gastrointestinal tract concerns colorectal cancer, where it is upregulated in response to IL-4 and IL-13 and involved in promoting proliferation, survival, migration, colony formation, and drug resistance." (PMID 32630408, 2020).
colorectal cancer (continued). "A recent study demonstrated that IL-13 can induce an aggressive type of colorectal cancer by enhancing the expression of the epithelial–mesenchymal transition-promoting factor ZEB1 through the STAT6-dependent pathway." (PMID 33352852, 2020). "In colorectal cancer, treatment with Claramine abolished IL-13-induced cell adhesion to Matrigel at a similar extent to the use of a blocking IL13Rα2 antibody (clone 47), suggesting that both treatments are likely blocking the same pathway." (PMID 32098194, 2020). "Increased expression levels of IL-13 have previously been observed in breast, oral squamous cell carcinoma and colorectal cancer." (PMID 33008336, 2020). "An increase was also observed for IL-13, which promotes cell migration and invasion in colorectal cancer." (PMID 30934926, 2019). "Different amounts of D1 peptide (from 10 ng/mL to 5 μg/mL) were tested to inhibit IL-13-mediated cell adhesion in metastatic KM12SM colorectal cancer cells." (PMID 30318506, 2018). "A growing body of evidence supports a role for the TH2-cytokines IL-4 and IL-13 in the pathogenesis of pre-malignant chronic inflammatory diseases of the gastrointestinal tract and in the enhancement of colorectal cancer cell proliferation." (PMID 28498822, 2017). "Elevated levels of IL-13 have been shown in colorectal cancer (CRC), we set out to determine the potential role of IL-13 in EMT induction in CRC cells." (PMID 27533463, 2016). "Both IL13 dose and receptors demonstrated that IL13 signal transduction was higher in the intestine but lower in colorectal cancer." (PMID 27708223, 2016). "IL-4, IL-5, and IL-13 are overexpressed in colorectal cancer (CRC)." (PMID 41155334, 2025). "However, under specific conditions, Th2 responses can exert anti‐tumor effects, as seen in colorectal cancer, where high IL‐13 expression correlates with improved survival." (PMID 41407509, 2025). "Furthermore, recent studies have demonstrated that IL-4 and IL-13, as well as the Type II receptor they share, are expressed widely in human colorectal cancers, as well as in a variety of other epithelial malignancies." (PMID 28498822, 2017). "IL-13 and IL-4 receptors may become attractive targets for the treatment of colorectal cancer." (PMID 37176567, 2023). "However, the influence of SNPs in microRNA-binding sites of the IL13 gene on the risk of colorectal cancer and overall survival has not been reported." (PMID 28537887, 2017). "Thus far, the exact role and mechanism of IL-13 in colorectal cancer (CRC) metastasis remain unclear." (PMID 27533463, 2016). "In summary, we have obtained an IL13Rα2-specific antibody 5.5.4 that can inhibit IL-13-mediated FAK, Src and AKT signaling to suppress metastatic liver colonization in colorectal cancer." (PMID 33917458, 2021). "The addition of HpARI in the medium significantly reduced the production of IL-13 by ILC2s, after co-culture with SW1116 colorectal cancer cells." (PMID 33953160, 2021). "The presence of a Th2 gene signature, which includes IL-4, IL-5, and IL-13, in human colorectal cancer does not appear to have prognostic significance." (PMID 41239618, 2025). "The authors observed increased expression of IL-10 and IL-13 and decreased expression of IL-1β, IL-6, interferon gamma (IFN-γ), TNF-α, IL-12, and IGF-1 in peripheral blood mononuclear cells (PBMCs) derived from patients with colorectal cancer." (PMID 38957737, 2024). "In addition, the inflammation molecules (IL-17, IL-2, IL-18, and IL-13) and oxidative stress capacity (GPx and SOD) were dysregulated in colorectal cancer as well as administration of 5-FU." (PMID 38637796, 2024).